TTR (transthyretin)
Diseases named in the same sentence as TTR in open-access papers (continued):
Sharing a sentence is not in itself a finding about the gene and the disease.
amyloidosis (continued). "Therefore age-related TTR oxidative modifications may play a role in the onset of ATTRwt amyloidosis." (PMID 36009453, 2022). "In ATTRwt amyloidosis, which was previously termed senile cardiac amyloidosis, a native non-mutated TTR protein misfolds into amyloid fibrils, primarily resulting in dysfunction of the heart that is characterized by restrictive cardiomyopathy; this is predominantly seen in males aged > 60 years." (PMID 33609196, 2022). "The endogenous expression of disease-associated, amyloidogenic TTR variants in induced pluripotent stem cell–derived hepatocytes increase expression of ATF6 and XBP1s target genes, suggesting an important role for UPR-dependent regulation of secretory proteostasis in TTR amyloid disease." (PMID 35191945, 2022). "Moreover, ex vivo cardiac fibrils from a human patient could work as a seed to facilitate TTR fibrillization even at physiological pH, raising the intriguing possibility that TTR amyloidosis may also involve nucleation, as many other amyloidogenic proteins do." (PMID 33922648, 2021). "Wild-type transthyretin (TTR) amyloidosis is increasingly being recognized and may be present in a quarter of the elderly at postmortem and is seen in 13–19% of patients with heart failure and preserved ejection fraction, likely making it the most common form of systemic amyloidosis." (PMID 33993188, 2021). "Interestingly, it has been postulated that vitreous ATTR has its own local source of TTR synthesis—the retinal pigment epithelium—which implies that vitreous amyloidosis may have different misfolding and aggregation pathways." (PMID 34880242, 2021). "As such, these symptoms may be most appropriately used to guide workup for amyloidosis in known V142I variant positive individuals, rather than to help identify candidates for TTR genetic testing." (PMID 33467513, 2021). "However, other toxic mechanisms of TTR amyloidosis have recently been described." (PMID 34884963, 2021). "Besides amyloidosis, TTR instability also leads to accelerated clearance, resulting in lower levels of the protein which in turn prevents TTR from fully exerting its functions, namely its neuroprotection roles, that will be further detailed ahead in this review." (PMID 32197355, 2020). "Since TTR mutations affecting amyloidosis become evident after the age of reproduction, no selective Darwinian pressure hindered acceptance and propagation of mutations that affect amyloidosis as long as the mutations had no substantial effect on transport functions." (PMID 33203794, 2020). "However, the safety and efficacy of TTR lowering as a therapeutic strategy have been validated by another therapy that reduces TTR levels using double-stranded RNAi (patisiran), which has recently been approved for the treatment of patients with hATTR amyloidosis with polyneuropathy." (PMID 32062791, 2020). "However, it should be noted that patients with exclusively ocular or central nervous system (CNS) complications can present with negative peripheral tissue biopsies, although they suffer from oculoleptomeningeal ATTRv amyloidosis, since there is a local production of TTR in the eye and in the CNS." (PMID 33032630, 2020). "In addition, the LNP technology was approved in 2018 for siRNA delivery as part of the product Patisiran (Onpattro, Alnylam Pharmaceuticals, Cambridge, MA, USA), which inhibits hepatocyte expression of transthyretin in patients with hereditary transthyretin-mediated amyloidosis." (PMID 32793245, 2020). "Finally, we discuss the way application of this model could change our understanding of the etiology and treatment of TTR amyloidosis specifically." (PMID 33203794, 2020). "In light of the negative ENDEAVOUR outcome, and notwithstanding the similarities in revusiran-mediated TTR reductions between those who died on drug versus those who did not, an important question arises regarding the safety of TTR-lowering approaches in hATTR amyloidosis." (PMID 32062791, 2020).
amyloidosis (continued). "Besides the well-known mechanisms of immune activation and inflammation in atherosclerosis causing ischemic cardiomyopathy or myocarditis, attention is focused on other mechanisms leading to heart failure such as transthyretin (TTR) amyloidosis or heart failure with preserved ejection fraction." (PMID 31083399, 2019). "However, in TTR amyloidosis, TTR gets fibrillized and deposited in organs forming the amyloid plaques which may trigger an organ dysfunction like PNS amyloidosis, CNS amyloidosis, cardiomyopathy, ophthalmopathy and nephropathy." (PMID 30704121, 2019). "However, how TTR fragments affect amyloidosis in vivo remains elusive." (PMID 30552363, 2018). "Amyloidosis, including neurodegenerative diseases such as Alzheimer’s disease or Parkinson’s disease as well as systemic diseases such as reactive systemic amyloidosis, TTR, and light chain amyloidosis are increasingly recognized as important death factors for public health systems." (PMID 31105169, 2017). "Based on these observations and since CtsE was found considerably reduced in injured V30M nerves, it is possible that this molecule might be involved in the mechanism contributing for the lower regenerative ability present in TTR V30M amyloidosis, which is under investigation." (PMID 28583160, 2017). "Since FAP and other TTR-related amyloidoses are progressive and complex multi-system disorders, therapeutic strategies aiming multiple molecular targets simultaneously, either through combination therapies or multi-target-directed compounds, could improve therapy efficacy and treatment outcome." (PMID 27197872, 2016). "Since non-mutated transthyretin also forms amyloid in systemic senile amyloidosis and some mutation bearers are asymptomatic throughout their lives, non-genetic factors must also be involved in transthyretin amyloidosis." (PMID 26147092, 2015). "However, distinctive phospho-tau aggregates were observed subjacent to the subpial TTR amyloid deposits in all regions of the neocortex, including the primary motor and striate cortices, suggesting a potential link between TTR amyloid and neocortical tauopathy." (PMID 26156087, 2015). "Thus, a nonhereditary, age-related form of TTR amyloidosis, senile systemic amyloidosis, is associated with WT TTR amyloid deposition in the heart, causing cardiac dysfunction." (PMID 24459092, 2014). "For example, in the amyloidosis of human transthyretin, the sequence-dependent unfolding pathway in these mutants may lead to the production of amyloidogenic intermediates, even though only minor structural differences between WT and disease-associated mutant proteins were found." (PMID 23559853, 2013). "Transthyretin (TTR) is a homotetrameric protein that circulates in plasma and cerebral spinal fluid (CSF) whose aggregation into amyloid fibrils has been associated with at least two different amyloid diseases: senile systemic amyloidosis (SSA) and familial amyloid polyneuropathy (FAP)." (PMID 23466880, 2013). "As an amyloidosis precursor, TTR could activate the unfolded protein (UPR), and other proteostatic responses thus inducing chaperone transcription, or activating stress related pathways, thus changing the protein homeostasis network to be more efficient in coping with Aβ aggregation." (PMID 22112803, 2011). "Misfolding of transthyretin (meningovascular amyloidosis), angiotensinogen, β2 – microglobulin, lysozyme, the Notch3 gene product, and the familial prion protein may each lead to amyloidosis." (PMID 16321154, 2005). "With regard to TTR, this approach might not only be of importance in the diagnosis of TTR related amyloidosis but may also have the potential as alternative or new biomarkers related to the metabolism of TTR for use in nutrition related disease as well as in the diagnosis of kidney function." (PMID 15341658, 2004).
amyloidosis (continued). "Among the various forms, cardiac involvement by transthyretin (ATTR) and immunoglobulin light chain (AL) amyloidosis is particularly significant, as it is the main determinant of prognosis and treatment." (PMID 41777219, 2026). "Over 30 types of amyloid proteins exist; however, the most clinically common ones, light chain (AL) and transthyretin (ATTR), are most prevalent, especially in developed countries, where almost all cases of amyloidosis are reported." (PMID 41356903, 2025). "The main types of amyloidosis include immunoglobulin light chain amyloidosis (AL amyloidosis), amyloid A (AA) amyloidosis and transthyretin (TTR) amyloidosis (hereditary or familial amyloidosis) formed from transthyretin." (PMID 40526695, 2025). "Therefore, the results might not be generalizable to patients with hereditary amyloidosis, especially considering the large number of TTR mutations and the variable cardiac and neurological phenotype of hereditary ATTR‐CM." (PMID 41168134, 2025). "The misfolding of wild-type TTR results in wild-type ATTR amyloidosis (ATTRwt amyloidosis), which presents as an acquired amyloid disease in the elderly." (PMID 40429804, 2025). "Transthyretin (ATTR) and immunoglobulin light chain (AL) amyloidosis represent the most common forms of CA." (PMID 40232627, 2025). "Predominantly (> 98%), amyloidosis manifests in two subtypes: light chain amyloidosis (AL), involving monoclonal immunoglobulin light chains, and transthyretin amyloidosis (TTR), involving transthyretin protein produced by the liver." (PMID 40114122, 2025). "We have identified a significant increase of SNCA, TTR, APOA1, and light chain variable of immunoglobulin protein, the proteins whose aggregation leads to different types of amyloidosis." (PMID 41379876, 2025). "The most prevalent amyloid protein in hereditary and senile amyloidosis is transthyretin (TTR), while dialysis-related amyloidosis primarily arises from impaired clearance and subsequent accumulation of β2-microglobulin (β2-MG) in vivo." (PMID 40901513, 2025). "Stabilizers work by binding to the TTR protein, preventing its misfolding or dissociation into monomers, which slows down the progression of ATTR-amyloidosis [7•, 51]." (PMID 38809394, 2024). "Among these, light chain (AL) and transthyretin (ATTR) amyloidosis are the most common forms in clinical practice, and distinguishing the type of amyloid is crucial since the differences in prognosis and treatment between the various types of CA are relevant." (PMID 39451564, 2024). "A kidney biopsy revealed extensive CR-positive fibrillary material, without IF reactivity for immunoglobulin heavy or LCs, protein A, or transthyretin, and mass spectrometry confirmed ALECT2 amyloidosis." (PMID 39356570, 2024). "Notably, a study that treated a transgenic mouse model for TTR-amyloidosis with carvedilol, a β-blocker with strong antioxidizing effects, found a reduction in both 4-hydroxy-trans-2-nonenal adducts and 8-hydroxy-2′deoxyguanosin adducts, as well as the total load of TTR deposits." (PMID 39615680, 2024). "The two most frequent subtypes of amyloidosis are transthyretin amyloidosis (ATTR) and light chain amyloidosis (AL), which are characterized by amyloid fibrils consisting of transthyretin and light chains, respectively." (PMID 39519011, 2024). "The TTR V142I (formerly V122I) mutation is prevalent in the black population (4%) and predisposes to the development of hereditary ATTR cardiac amyloidosis – the clinical syndrome overlaps that of wtATTR amyloidosis although the disease phenotype may be more aggressive." (PMID 38275011, 2024). "Several subtypes of amyloidosis exist, such as light-chain amyloidosis, serum amyloid A protein, transthyretin (TTR) amyloidosis, beta-2 microglobulin amyloidosis, and apolipoprotein A1 or A2 amyloidosis." (PMID 39791066, 2024).
amyloidosis (continued). "However, as we did not perform specific diagnostic tests for transthyretin amyloidosis, we cannot provide data on patients with low transthyretin levels who may have been diagnosed with amyloidosis during follow-up." (PMID 39478501, 2024). "The protein transthyretin (TTR), which is responsible for amyloidosis, is reportedly involved in LF hypertrophy." (PMID 37973808, 2023). "We therefore performed sequential ECV quantification using CMR T1 mapping and evaluated the prognostic impact of its changes on outcome in treated, as well as treatment-naïve, transthyretin (ATTR) and light chain (AL) amyloidosis patients." (PMID 37549339, 2023). "IHC-based amyloid typing is used in most medical centers by employing commercial antibodies to the precursor proteins of the most common forms of amyloidosis, i.e., antibodies to κ and λ light chains, SAA, and TTR." (PMID 36902083, 2023). "The progressive accumulation of transthyretin (TTR),a small proteinthat transports thyroxine, in various organs and tissues is observedupon transthyretin amyloidosis, a severe pathology that affects thecentral, peripheral, and autonomic nervous systems." (PMID 37676231, 2023). "The major types of systemic disease result from the misfolding and aggregation of transthyretin (ATTR amyloidosis), free monoclonal immunoglobulin light chains (AL amyloidosis) or leukocyte cell-derived chemotaxin-2 (ALECT2 amyloidosis)." (PMID 37854603, 2023). "One of the therapeutic approaches against TTR amyloidosis (ATTR) progression is the use of small molecules that are able to bind the T4BP, which contributes to the stability of the TTR tetramer." (PMID 36771455, 2023). "There are several histological forms of amyloidosis: transthyretin (TTR) amyloidosis (ATTR) and amyloid light-chain (AL) amyloidosis are the most frequent." (PMID 37926810, 2023). "How WT transthyretin leads to amyloid deposition in senile cardiac amyloidosis is unclear, but a transgenic mouse model with TTR overexpression demonstrated amyloid deposition." (PMID 35104251, 2022). "By targeting the TTR mRNA, vutrisiran is able to reduce TTR protein expression, leading to better outcomes in patients with ATTR-mediated amyloidosis." (PMID 35269876, 2022). "For patients with hereditary transthyretin (TTR)–related amyloidosis, the FDA has approved pharmacotherapy with TTR-stabilizing agents only for TTR cardiac amyloidosis." (PMID 35363504, 2022). "Vutrisiran is a transthyretin-directed siRNA therapeutic for the treatment of amyloid transthyretin-mediated (ATTR) amyloidosis, including hATTR amyloidosis and wild-type ATTR (wtATTR) amyloidosis." (PMID 36588695, 2022). "A prominent example is transthyretin (TTR), a transport protein that is itself related to amyloid disease upon destabilization of its native tetrameric state." (PMID 36115577, 2022). "Diagnosis of ATTRv amyloidosis relies on sequencing of the whole TTR gene, which is mandatory even in bioptically confirmed cases to distinguish between ATTRv and wildtype ATTR (ATTRwt) amyloidosis because of different treatment approaches." (PMID 36494773, 2022). "Transthyretin (TTR), the precursor protein for amyloidogenic TTR (ATTR) amyloidosis, forms tetramers and escapes glomerular filtration by binding with thyroxine and retinol-binding protein." (PMID 35893595, 2022). "The release of monomers from the homotetrameric protein transthyretin (TTR) is the first event of a cascade, eventually leading to sporadic or familial TTR amyloidoses." (PMID 35337074, 2022). "Therefore, pharmacologically enhancing the degradation of TTR aggregates and kinetically stabilizing the native tetrameric structure with bioactive molecule(s) could be a viable therapeutic strategy to hinder the advancement of TTR amyloidoses." (PMID 35784752, 2022). "Inotersen (Tegsedi), a 2MOE ASO designed to reduce the production of TTR, was approved by the FDA in 2018 for the treatment of all forms of TTR amyloidosis." (PMID 33996898, 2021).
amyloidosis (continued). "For example, tolcapone, the approved drug molecule for Parkinson’s disease, was shown to bind to TTR tetramer better than tafamidis and exhibit superior BBB permeability, thus being a strong therapeutic candidate for TTR amyloidosis." (PMID 33800546, 2021). "Because NEP and TTR both degrade Aβ, we expected that AICD SUMOylation would decrease the amount of Aβ and amyloid plaques." (PMID 32950104, 2021). "Wild-type TTR amyloidosis (ATTRwt), formerly known as senile systemic amyloidosis (SSA), is an idiopathic disease characterized by the deposition of wild-type (wt) TTR amyloid mainly in the heart." (PMID 35008816, 2021). "Transthyretin, a circulating protein which is synthesized in the liver and is responsible for the transport of thyroxine and retinol binding protein, may form amyloid when unmutated with advancing age (wild-type ATTR amyloidosis) or in association with over 130 genetic variants." (PMID 34957240, 2021). "Therefore, TTR may be useful in preventing or treating amyloidosis." (PMID 33256250, 2020). "Next, we assessed the presence of TTR and APP as well as amyloid structures in human CAVD tissue by immunohistochemistry and histology." (PMID 32987857, 2020). "However, TTR itself might undergo protein misfolding and aggregation leading to TTR amyloidosis." (PMID 30510498, 2018). "Of the other measures taken in APOLLO, a correlation between mNIS+7 and TTR knockdown was demonstrated in the Phase 2 open-label extension study of patisiran, supporting the hypothesis that reducing levels of amyloidogenic protein leads to clinical benefit in hATTR amyloidosis (e.g., via OLT)." (PMID 28893208, 2017). "We describe here how the application of a drug repositioning protocol for the TTR amyloidoses has crystallized in the discovery of tolcapone, a promising FDA-approved drug for the treatment of SSA, FAP, FAC and uniquely, TTR leptopmeningeal amyloidosis." (PMID 26902880, 2016). "From TTR stabilizers (diflunisal, tafamidis), gene therapies to suppress TTR expression (siRNAs) and amyloid fibrils disruptors (doxycycline/TUDCA), the perspectives for an effective therapy for TTR amyloidosis seem more encouraging nowadays than ever before." (PMID 27197872, 2016). "Recent studies reported that certain Swedish patients with late-onset FAP ATTR Val30Met have amyloid deposits containing truncated TTR, which is usually found in SSA, a sporadic form of TTR amyloidosis." (PMID 25228988, 2014). "For example, FLP binds to TTR, COX-1 and COX-2 with similar sets of interactions and inhibits both TTR amyloidosis (70% inhibition at 7.2 μM), COX-1 (IC50 = 0.41 μM) and COX-2 (IC50 = 4.2 μM) enzyme activity." (PMID 19621084, 2009). "Current diagnostic algorithms for cardiac amyloidosis increasingly favor non-biopsy strategies, particularly for transthyretin (ATTR) amyloidosis." (PMID 41596468, 2026). "Myocardial scintigraphy and genetic exams were even performed to rule out transthyretin (ATTR) amyloidosis." (PMID 40182311, 2025). "Nonetheless, both ATTR-CM patients without increased LVWT exhibited other typical red flags indicative of transthyretin amyloidosis." (PMID 40293703, 2025). "Furthermore, amongst currently available agents for the use of TTR amyloid disease, it is the only therapeutic that has a dual indication for both neuropathy and cardiomyopathy, which are found concomitantly in many, if not most, hereditary or variant TTR patients." (PMID 40943848, 2025). "The 2 most common forms of amyloidosis are AL (light chain) and ATTR (transthyretin)." (PMID 40448354, 2025). "Irrespective of TTR genotype, most patients with ATTRv amyloidosis develop a mixed phenotype of polyneuropathy and cardiomyopathy in addition to manifestations in other systems such as gastrointestinal disturbance and autonomic neuropathy." (PMID 40974604, 2025).